MMP2 (matrix metallopeptidase 2)
Diseases named in the same sentence as MMP2 in open-access papers (continued):
Sharing a sentence is not in itself a finding about the gene and the disease.
cancer (continued). "Multifunctional effects of EGCG in downregulation of MMP-2 by interfering with the activation, secretion, and regulation of the molecule have been demonstrated in many cancer cell types such as breast, oral, lung, and others." (PMID 25184134, 2014). "The expression of MMP2 was downregulated significantly (P<0.05) in CS-silenced cancer cells as shown by western blot." (PMID 25545012, 2014). "IL-17A was reported to promote the invasion of cancer cells via up-regulating the expression of MMP-2/-9." (PMID 25244643, 2014). "These anti-malignant phenotypes of L1CAM-knockdown cancer cells were accompanied by G0/G1 cell cycle arrest and suppression of matrix metalloproteinase (MMP)-2 and MMP-9 expression and nuclear factor NF-κB activation." (PMID 25294816, 2014). "Molecules such as Her2, EGFR, VEGFR, ALK, AKT, p52, cyclin D1, Met, Cdk4, HIF-1α or MMP2 which play important roles as oncogenes and are involved in essential pathways of cancer are described to be client proteins of HSP90." (PMID 24978439, 2014). "In summary, we have identified myeloid cells that express CCR1, MMP9 and MMP2 to promote cancer metastasis." (PMID 25326065, 2014). "The result showed that, CDH1, VEGFA, PTPRF and CLDN7 were up-regulated in six cancer samples, and MMP2 was down-regulated in ten cancer samples, suggested that these genes, especially MMP2, were dysregualted in most UCB samples." (PMID 24622401, 2014). "The activated MMP-2 expression was also correlated with cancer cell invasion and metastasis in various cancers." (PMID 25184134, 2014). "MMP-2 and MMP-9 play important roles in cancer metastasis, and IL-17A can affect the expression of MMP-2 and MMP-9." (PMID 25244643, 2014). "Among these proteases, the levels of MMP-2 and MMP-9 are high in various malignant tumors and are closely associated with the ability of cancer cells to invade and metastasize." (PMID 25036034, 2014). "This inhibitory effect of administrated siRNA on L1CAM expression was strictly associated to decreased IHC staining of MMP-2, MMP-9 and NF-κb in cancer cells." (PMID 25294816, 2014). "This will provide a basis for the responsive theragnostic platform in which the therapeutic payload is preferentially delivered to tumors with high activity of MMP2 enzymes (i.e. containing highly metastatic cancer cells)." (PMID 24919932, 2014). "Previous studies have suggested that the ERK1/2 pathway increases the invasion of several cancers by increasing MMP-2/9 expression and activity." (PMID 24931737, 2014). "In this study we tested the feasibility and usefulness of our novel drug design strategy wherein the MMP-2 activity-dependent anchoring probe MDAP is used for MMP-2 activity imaging in cancer." (PMID 25010662, 2014). "It is reported that inhibition of extracellular HSP70 and HSP90 reduce MMP-2 activation and decrease cancer cell migration and invasion." (PMID 25175595, 2014). "It should be noted that FoxM1 is a transcription factor that regulates MMP-2 expression, suggesting that OGT regulates cancer cell invasion by modulating MMP-2 expression." (PMID 24918087, 2014). "Measurements of the expression of RECK and MMP-2 are valuable, not only to assess patient prognosis, but to also develop new strategies for cancer prevention and therapeutic intervention." (PMID 24765174, 2014). "MMP2 and MMP9 were selected as they have previously been implicated in the invasive ability of cancer cells." (PMID 24348851, 2014). "Consistent with the results obtained in cancer, the upregulation of MMP-2 and MMP-9 also contributes to the migratory/invasive behavior of human mesenchymal stem cells (hMSC)." (PMID 24804928, 2014). "Most significantly, MMP2 and MMP9 have been reported to cause invasion and metastasis in various cancers." (PMID 24348851, 2014). "EMMPRIN has been well demonstrated to enhance cancer cell invasion in several human malignancies by increasing the expression of the extracellular signaling molecules MMP-2 and uPA." (PMID 24705283, 2014).
cancer (continued). "Pretreatment with MG132 followed by irradiation in dose of 4 Gy in vitro is shown to suppress cell migration and invasion abilities in A549 and H1299 cancer cell lines, which is accompanied by decreased expression of MMP-2 and MMP-9 in NSCLC cell lines." (PMID 25302298, 2014). "MMP2 and MMP9 are two of the most well-characterized MMPs and are closely associated with cancer invasion and metastasis due to their strong proteolytic activity of ECM." (PMID 24479681, 2014). "Ultrasound combined with microbubbles inhibited the activities of MMP-2 and -9, which are involved in the degradation of the extracellular matrix and thus, are important in cancer cell migration and invasion." (PMID 25120726, 2014). "Critical involvement of CCR1, MMP9 and MMP2 was verified experimentally using gene knockout mice lacking these proteins, which suggested possible therapeutic intervention of cancer progression by targeting these molecules." (PMID 25326065, 2014). "It is postulated that fibroblast derived MMP-2 is activated by a factor secreted from the cancer cell called EMMPRIN, an extracellular matrix metalloproteinase inducer." (PMID 24591757, 2014). "Serum levels of MMP-2 were significantly higher in patients with positive expression of this protein in cancer cells (p = 0.047) as well as in patients with positive expression of TIMP-2 in inflammatory (p < 0.001) and normal colorectal cells (p = 0.04)." (PMID 24395652, 2014). "We demonstrated that MMP-2 serum levels were significantly higher in patients with positive expression of this enzyme in cancer cells and in CRC patients with positive expression of TIMP-2 in inflammatory and normal cells." (PMID 24395652, 2014). "MMP-2/9, secreted and activated by cancer cells, hydrolyze the basement membrane and ECM, which facilitates the invasion of malignant cells and results in metastasis." (PMID 24618693, 2014). "The engineered protein nanocages showed a binding affinity for MMP-2 and selective uptake in cancer cells that highly expressed MMP-2 in vitro." (PMID 25547485, 2014). "IL-17A has been reported to promote the invasion of cancer cells via upregulating the expression of MMP-2 and MMP-9." (PMID 24905806, 2014). "Elevated plasma levels of soluble gelatinases, including MMP-2 and -9, have been positively correlated with a higher incidence of metastases in different types of cancer and have been considered as a valuable prognostic factor in breast and colon cancer." (PMID 25013462, 2014). "MMP-9 and MMP-2 are important ECM-degrading enzymes that are involved in cancer invasion and metastasis." (PMID 25174454, 2014). "A growing body of evidence suggests that MMPs, particularly MMP-2, is upregulated in malignant tumors and contributes to the invasion and metastatic spread of cancer cells by degrading type IV collagen, a major component of the basement membrane." (PMID 24715095, 2014). "High levels of MMP-2 expression have been demonstrated in many different cancers, including the liver, lung, colon, breast, prostate, skin, and ovary." (PMID 25184134, 2014). "PEA3 mRNA expression in stromal cells was significantly related to MMP-2 mRNA expression in carcinoma cells, whereas PEA3 expression in carcinoma cells was significantly related to mRNA expression of the β1 integrin subunit, bFGF, and EMMPRIN in stromal cells." (PMID 24860785, 2014). "HER2/neu has been reported to enhance the metastatic potential of cancers cells and is positively correlated with MMP-2 expression." (PMID 23922932, 2013). "In conclusion, we showed that Bmal1 attenuates cancer cell invasion by suppressing the PI3K-Akt-MMP-2 pathway." (PMID 23563360, 2013). "Our data clearly demonstrates that fumigaclavine C can inhibit MMP-2 and -9, which are known to be highly expressed in invasive cancer cells while suppressing the survival of cancer cell." (PMID 24351905, 2013).
cancer (continued). "Claudin-4 has been shown to activate MMP-2 and claudin-4 expression has been significantly associated with MMP-9 expression, indicating that claudin-mediated increased cancer cell invasion result from activation of MMP proteins." (PMID 23919729, 2013). "Polymorphisms in the MMP1, MMP2, MMP3, and MMP9 genes have been examined in studies evaluating cancer metastasis and functional polymorphisms have been identified for these genes." (PMID 23696797, 2013). "B7-H3 and matrix metalloproteinases 2 (MMP-2) are reported highly expressed in malignant tumor, we investigate the relationship between B7-H3 expression and MMP-2 on malignant behavior and prognosis predictable value in pancreatic cancer." (PMID 23947693, 2013). "A previous study of the comparative effects of NM, green tea extract and EGCG on inhibition of MMP-2 and -9 secretion of different cancer cell lines with varying MMP secretion patterns, revealed the superior potency of NM over GTE and EGCG at equivalent doses." (PMID 23563849, 2013). "MMP-2, as a predictor of recurrence and metastasis in cancer, was also found downregulated in McA-SYYCM cells." (PMID 23622143, 2013). "The epithelial-mesenchymal transition (EMT), cancer stem cell markers, and cancer metastasis associated proteins such as Snail, Twist, CD133, and matrix metalloproteinase 2 (MMP-2), MMP-9 were differentially expressed in these two cell s." (PMID 23382894, 2013). "MMP-2 and MMP-9 are the most extensively studied of the MMP family because of their high association with cancer migration and invasion." (PMID 23799155, 2013). "Together these observations suggest that the role played by p21 and MMP-2 are important in inhibition of cancer cells." (PMID 23887718, 2013). "It is a serine protease that converts plasminogen to plasmin, which directly mediates cancer cell invasion by degrading matrix proteins such as collagen IV, fibronectin, and laminin or indirectly by activating MMP-2, MMP-3, MMP-9, and uPA." (PMID 23878609, 2013). "At the molecular level, MMP2, MMP7 and MMP9 are associated with cell migration process, influencing cancer development and progression." (PMID 24098538, 2013). "Several previous studies have indicated that natural products inhibit cancer metastasis by inhibiting MMP-2 and MMP-9 expression." (PMID 23799155, 2013). "As MT1-MMP is bound to cancer cells, its region of proteolytic activity is more restricted than that of the freely diffusive proteolytic enzyme MMP-2." (PMID 23565505, 2013). "Some ganoderic acids and lucidenic acids have been reported to exert anti-invasive effect via suppression NF-κB signaling and down-regulation the expressions of MMP-9, MMP-2, uPA, and uPAR in various cancer cells." (PMID 24204647, 2013). "Although the molecular mechanisms of PDPN expression in CAFs are not clear, and CAFs have functional heterogeneity, we found that PDPN+ CAFs play an important role in cancer cell invasion in association with the expression of CD10, MMP2, and MMP3." (PMID 24354864, 2013). "Overexpression of basigin-2 increased the secretion of MMP-2/9 and cancer cell migration and invasion of HO-8910 cells, whereas knockdown of basigin-2 reduced active MMP-2/9 production, migration and invasion of HO-8910 PM cells." (PMID 23566400, 2013). "Our results agree with previous studies showing that blocking IL-6 attenuates cancer cell invasiveness through down regulation of MMP-2 and MMP-9 expression." (PMID 23593315, 2013). "MMP-2 and MMP-9 were reported to be associated with the invasion and metastasis of many malignant tumors." (PMID 23613942, 2013). "We observed that the AMPK inhibitors, namely, Ara A and compound C, antagonize CCL3-mediated cancer migration and MMP-2 expression, suggesting that AMPK activation is an obligatory event in CCL3-induced migration activity in these cells." (PMID 24047437, 2013).
cancer (continued). "Its overexpression has been found to be associated with up-regulation of MMP-2 and MMP-9 that play an important role in cancer cell invasion and metastasis." (PMID 23922932, 2013). "As MMP-2 and MMP-9 are the downstream targets of β-catenin, and play a role in cancer cell metastasis, we also examined the effect of honokiol on the levels of MMP-2 and MMP-9 in NSCLC cell lines." (PMID 23580348, 2013). "Overexpression of various MMPs, particularly MMP-2, is correlated with poor prognosis in many types cancer including adrenocortical cancer, breast cancer, and thyroid malignancies." (PMID 23947693, 2013). "Particularly, MMP-2 (gelatinase-A) and MMP-9 (gelatinase-B) are highly expressed in epithelial cancer cells and involved in epithelial-mesenchymal transition (EMT) implicated in cancer invasion and metastasis." (PMID 24018886, 2013). "The MMP family has 29 members; among these members MMP-2 and MMP-9 were found to have increased enzymatic activity and associations with metastasis in several cancers including NPC." (PMID 24243817, 2013). "MMP-2 is associated with local infiltration, while MMP-9 is the main participant in cancer recurrence and metastasis." (PMID 24137293, 2013). "Bcl-w protects cells from apoptotic stimuli and also promotes the invasion of cancer cells by activating the PI3K-Akt-MMP-2 pathway." (PMID 23563360, 2013). "Among the variety of MMPs, MMP2, MMP7, and MMP9 were more commonly associated with cancer metastasis as they have the ability to degrade collagen type IV which is the major component of basement membrane." (PMID 24138815, 2013). "The 2Chr7:1n,1d cells exhibited a more invasive phenotype by expressing higher levels of the pro-invasive genes (IGFBP2, PDGFRA, RHOC, FOXM1, and PLAU) and matrix metalloproteinase 2 (MMP2), all of which are well-reported for cancers, including GBM." (PMID 24282558, 2013). "The extracellular matrix proteins such as MMP-2 and MMP-9 which play an important role in cell migration and inflammatory processes associated with various cancers are highly induced in vehicle-treated xenograft tumors." (PMID 24260338, 2013). "Among these MMPs, matrix metalloproteinase-2 (MMP2) has been considered critical for cancer invasion and metastasis." (PMID 24341487, 2013). "Soy saponins were also found to have cancer-protecting ability by reducing the expression of mRNA and the amount of matrix metalloproteinases (MMP-2 and MMP-9) in HT-1080 cells." (PMID 24224098, 2013). "Previous studies have indicated that the AKT/SP-1 pathway regulated MMP-2 promoter activity and affected the migration ability of cancer cells." (PMID 23799155, 2013). "Other molecule promoting cancer cells migration and invasion like c-Met, MMP2, MMP9 were assessed by western blot." (PMID 24180482, 2013). "Among the MMPs family, MMP2 and MMP9 were more commonly associated with cancer invasion and metastasis since they had been known to be able to degrade type IV collagen-rich basement membrane of vessel wall." (PMID 24138815, 2013). "Although various MMPs contribute to cancer cell metastasis, the gelatinases MMP-2 and MMP-9 have been most intensively studied." (PMID 23799155, 2013). "MMP2 and MMP9 were significantly associated with cancer-related pathways, which further illustrates the potential of rhein and its products to be used for cancer relief in China." (PMID 23983798, 2013). "MMP-2 is one of the most vital proteins for degradation of the main constituent of the basement membrane and therefore involved in cancer invasion and metastasis." (PMID 23667687, 2013). "In this study, to investigate the protective effect of piceatannol against cancer metastasis, we first examined the inhibitory effect of piceatannol on MMP-2 upregulation in H-ras MCF10A cells." (PMID 23877152, 2013). "In this paper, we apply a reduced form of the activation system of MMP-2 to our model of cancer cell invasion where tissue degradation is mediated by either MT1-MMP or MMP-2." (PMID 23565505, 2013).
cancer (continued). "In summary, our results strongly indicates the potential of PA as an potential anti-cancer agent, with its multipotential effects in inhibiting survival and proliferation of A549 cells, chemoinvasion, and secretion and activation of MMP-2." (PMID 23887718, 2013). "Activation of both PI3K/Akt pathway and MMP-2 are known to increase cell migration and invasion, leading to metastasis in various cancers." (PMID 23817777, 2013). "In 1 month following the operation, the highest level of MMP-2 was also in patients with unresectable cancer and the highest level of TIMP-2 in patients with inflammatory tumors." (PMID 23768069, 2013). "All together, our data suggest that miR-29b is critical for HAG to suppress the MMP-2 expression in cancer cells." (PMID 24130681, 2013). "It has been found that metalloproteinase MMP-2 is responsible for increased invasiveness while MMP-9 expression in carcinoma cells offers survival advantage." (PMID 24351905, 2013). "Despite a strong stimulation of pericellular MMP-2 and uPA proteolytic activities, carcinoma cell invasion decreased by LRP-1 silencing." (PMID 23936774, 2013). "Previous studies have also identified significantly increased urine and plasma MMP-2 concentrations in cancer patients, with MMP-2 and MMP-9 being considered as predictors of risk or recurrence of metastasis or as cancer prognostic markers." (PMID 23320037, 2012). "Within the spheroids the cancer cells maintain a epithelial phenotype and express Sip 1, a regulator of E-cadherin and matrix metalloproteinase (MMP-2)." (PMID 22888339, 2012). "Fucoidan treatment of non-toxic dose (0–200 μg/ml) exhibits a concentration-dependent inhibitory effect on the invasion and migration of the cancer cell via decreasing its MMP-2 activity." (PMID 23226337, 2012). "Like MMP-14, MMP-15 has been most widely studied for its role in cancer progression and metastasis, primarily through its capacity to cleave and activate MMP-2." (PMID 22768148, 2012). "This crosstalk between stromal and cancer cells would explain the differences in MMP-2 expression found in the three groups of patients." (PMID 23227342, 2012). "Amongst the MMP family members, MMP-2 and -9 are generally considered to be the malignancy of various tumors as well as poor prognosis of many cancers." (PMID 22962598, 2012). "Amongst the MMPs, gelatinases MMP-2/9 show dominant role in cancer progression, indicating the potential of MMP-2/9 as therapeutic target in the prevention of cancer metastasis." (PMID 23029478, 2012). "By comparison, in mucosa from fibrotic CD, there was a significant increase in collagen synthesis and MMP-2 compared to cancer controls (p<0.02) and compared to uCD (p<0.01), and pro-MMP-2 levels did correlate with collagen synthesis (p = 0.003)." (PMID 23300643, 2012). "Generally, MMP-2 is over-expressed constitutively in highly metastatic cancers, whereas MMP-9 is induced by some stimulating factors such as inflammatory cytokines, epidermal growth factor and phorbol-12-myristate-13-acetate." (PMID 23226337, 2012). "The result of this study's showed that CAPE significantly inhibited the migratory/invasive ability of SCC-9 cancer cells, downregulated MMP-2 protein expression, and inhibited MMP-2 enzymatic activity." (PMID 23320037, 2012). "Genes that have been previously associated with MD and various other cancers showed differential marks that are either MD-induced (MX1, CTLA-4, EAF2 and GAL) or line-specific (IGF2BP1 and MMP2)." (PMID 23072359, 2012). "For example, MMP-2 signal was shown to be present in 76% of malignant tumors and 54% of benign tumors on immunohistochemical analysis." (PMID 22200690, 2012). "A number of cancer molecular markers associated with bone metastasis were assessed by immunohistochemical technique, including PTHrP, OPN, c-Src, MMP2, CXCR4, PI3K, BSP, NFκB, IGF-1R, and BMP4." (PMID 22537906, 2012).